LINC-ROR (long independently transcribed non-coding RNA, regulator of reprogramming)
Diseases named in the same sentence as LINC-ROR in open-access papers (continued):
Sharing a sentence is not in itself a finding about the gene and the disease.
colon cancer (11 papers, 2015 to 2024). "The LINC-ROR rs1942347*A variant was associated with an earlier onset of colon cancer in a dose-dependent manner (p = 0.039)." (PMID 35454158, 2022). "Our study, for the first time, reports the association of the LINC-ROR rs1942347 variant with poor colon cancer outcomes." (PMID 35454158, 2022). "A different approach was carried out in 351 paraffin-embedded blocks of colon cancer tissue specimens to identify the presence of genomic variants of linc-ROR; the rs1942347*A allele variant was associated with high pathological grade, larger tumor size, distant metastasis, and mortality." (PMID 36827545, 2023). "A positive correlation was found between linc-ROR and epidermal growth factor receptor (EGFR) signaling in colon cancer, in which linc-ROR served as a tumor-promoting factor via repressing the ubiquitination and degradation of EGFR signaling." (PMID 36827545, 2023). "The differential expression of MEG3 and linc-ROR between colorectal cancer cells and HeLa cells indicates that the bidirectional CEA promoter exerts a specific regulatory effect on gene expression in colon cancer, establishing it as a promising tumor-specific promoter." (PMID 39108882, 2024).
liver cancer (11 papers, 2016 to 2023). An epithelial or non-epithelial malignant neoplasm that arises from the liver. "It was reported that LINC-ROR promote liver cancer stem cell growth by upregulating TERT and C-MYC." (PMID 31890219, 2019).
glioma (10 papers, 2015 to 2022). A benign or malignant brain and spinal cord tumor that arises from glial cells (astrocytes, oligodendrocytes, ependymal cells). "One study reported that linc‐ROR expression was significantly down‐regulated in glioma tissues compared to that in adjacent tissues and that its silencing significantly enhanced the proliferation of glioma cells and the spheronization of GSCs." (PMID 30117678, 2018). "However, the role of Linc-ROR in glioma is the opposite of other tumors." (PMID 29549263, 2018). "On the other hand, the underexpression of LINC-ROR is correlated with the mRNA expression levels of SOX11 and KLF4 in glioma." (PMID 33745265, 2021).
colorectal cancer (8 papers, 2018 to 2024). A primary or metastatic malignant neoplasm that affects the colon or rectum. "In colorectal cancer samples, linc-ROR and the oncogenic lncRNA colon cancer-associated transcript 1 (CCAT1) were upregulated and significantly associated with synchronous metastases." (PMID 36827545, 2023). "Dysregulation of long noncoding RNAs (lncRNAs), such as maternally expressed gene 3 (MEG3) and long intergenic noncoding RNA regulator of reprogramming (linc-ROR), plays a crucial role in colorectal cancer progression." (PMID 39108882, 2024). "Aberrant activation of the Wnt/β-catenin signalling pathway has been reported in colorectal cancer, and our previous study also demonstrated that lincROR activated the Wnt/β-catenin signalling pathway during pathogenesis of mesenchymal stem cells." (PMID 39546475, 2024). "Breast and colorectal cancers are two of the most prevalent cancers worldwide, which has driven investigators to try to find the relationship between linc-ROR and the proliferation and progression of these cancers." (PMID 36827545, 2023). "In colorectal cancer, 52 tissue samples were analyzed to observe a positive correlation between linc-ROR expression and tumor size, lymph node involvement, and distant metastasis." (PMID 36827545, 2023). "Interestingly, a significant differential expression of MEG3 and linc-ROR was observed only in colorectal cancer cells." (PMID 39108882, 2024). "Another research performed in both breast and colorectal cancer found that linc-ROR increases c-Myc whilst interacting with the heterogenous nuclear ribonucleoprotein 1 (hnRNP1) and the AU-rich element RNA-binding protein 1 (AUF1), promoting cell proliferation and tumorigenesis." (PMID 36827545, 2023). "Moreover, the gene ROR was reported to be associated with the development of TGF-β induced tumors, we justly wondered whether this lincROR could act as a therapeutic target for TGF-β related colorectal cancer." (PMID 39546475, 2024). "Therefore, LincROR has the potential to be a therapeutic target for colorectal cancer." (PMID 39546475, 2024). "In another experiment involving stem cells in colorectal cancer (CRC), it was found that linc-ROR functions as a key ceRNA to prevent core transcription factors from miR-145-mediated suppression, regulating cell proliferation." (PMID 36827545, 2023).
gastric cancer (8 papers, 2015 to 2024). A primary or metastatic malignant neoplasm involving the stomach. "A probable function interaction between the spalt-like transcription factor 4 (SALL4) and linc-ROR was associated with tumor maintenance and aggressiveness in gastric cancer (GC) tissues with helicobacter pylori infection." (PMID 36827545, 2023). "For instance, lincROR is upregulated in gastric carcinoma and promotes cancer cell proliferation and metastasis." (PMID 39546475, 2024). "A study with gastric cancer samples and cell lines revealed that linc-ROR led to the upregulation of several key stemness transcriptional factors such as OCT4, SOX2, Nanog, and CD133, promoting proliferation and invasion of gastric cancer stem cells." (PMID 36827545, 2023). "Intriguingly, linc-ROR expression in gastric cancer has evidenced mixed results." (PMID 36827545, 2023). "In addition, the mechanism of linc-ROR in gastric cancer is unclear." (PMID 33163123, 2020). "In gastric cancer cell lines MKN45 and HGC-27, linc-ROR acted in the miR-519-d-3p/HMGA2 network to promote cisplatin resistance, whilst the same resistance was demonstrated in osteosarcoma samples via miR-153-3p/ABCB1 axis." (PMID 36827545, 2023). "In gastric cancer cells resistant to Adriamycin (ADR) and vincristine (VCR), linc-ROR was upregulated, and with its depletion, reduced MRPI expression and increased apoptosis of drug-resistant cancer cells." (PMID 36827545, 2023). "Another explored axis that promotes EMT in gastric cancer involved the sequestering of miR-212-3p by linc-ROR to express the fibroblast growth factor 7 (FGF7), contributing to promoting migratory and invasive capabilities of gastric cancer cell lines." (PMID 36827545, 2023). "Conversely, the expression levels of linc-ROR- HOXA-AS2, and MEG2 were lower in gastric cancer samples compared to non-cancerous samples." (PMID 36827545, 2023).
nasopharyngeal carcinoma (8 papers, 2018 to 2024). A carcinoma arising from the nasopharyngeal epithelium.
endometrial cancer (7 papers, 2017 to 2025). Primary or metastatic malignant neoplasm involving the endometrium (mucous membrane that lines the endometrial cavity). "Linc-ROR has been identified as an upstream modulator or a downstream effector of major signaling pathways influencing endometrial cancer metastasis, including the AKT/PI3K signaling pathway." (PMID 34447693, 2021). "Linc-RoR functioned as a miR-145 sponge by repressing the miRNA-mediated degradation of core stem cell transcription factors (i.e., Nanog, Oct4, and Sox2), thereby maintaining the pluripotency of endometrial cancer stem cells." (PMID 29147648, 2017). "LncRNAs that play a role in tumor suppression in endometrial cancer include: FER1L4, GAS5, MEG3, RP11-395G23.3, LA16C −313D11.11, Xist, Linc ROR, MALAT1, HOTAIR, OVAL, SRA, etc., However, the mechanism of cuproptosis-associated LncRNAs in endometrial cancer is still unclear." (PMID 37124623, 2023). "In endometrial carcinoma, a distinct regulatory pattern was observed, with LINC00582, LINC-ROR, MEG3, NEAT1, and SNHG12 displaying significant negative correlations." (PMID 41303609, 2025). "Linc-ROR/miRNA axis-mediated SOX9 activation might not be the only mechanism for regulating cancer stemness in ESCC, given that miR-145 has also been reported to enhance aggressive phenotypes by targeting NANOG in pancreatic and endometrial cancer." (PMID 29237490, 2017).
bladder cancer (6 papers, 2017 to 2025). "Several studies in kidney and bladder cancer agree in positioning linc-ROR as a tumor promoter through different pathways and molecular functions." (PMID 36827545, 2023). "Increased LINC-ROR expression was found in bladder cancer tissues and cell lines, leading to the induction of EMT, promotion of cell proliferation, migration, invasion, and tumor progression." (PMID 33745265, 2021). "Recent studies have displayed that the level of linc-ROR was increased in lung cancer, bladder cancer, and CRC cell lines." (PMID 32850817, 2020). "In bladder cancer tissue samples and cell lines, ZEB1 was a target gene of linc-ROR, promoting tumor cell proliferation and inhibition of cell apoptosis." (PMID 36827545, 2023).
lung adenocarcinoma (6 papers, 2017 to 2023). A carcinoma that arises from the lung and is characterized by the presence of malignant glandular epithelial cells. "Surprisingly, linc-ROR expression increased the sensitivity of lung adenocarcinoma cells to cisplatin by targeting the PI3K/Akt/mTOR signaling pathway." (PMID 36827545, 2023). "The knockdown of Linc‐ROR led to the decrease of EMT of docetaxel‐resistant lung adenocarcinoma cells to sensitize drug‐resistant cells to chemotherapy." (PMID 29663730, 2018). "The same linc-ROR/miR-145 axis overexpressed the fascin-acting-bundling protein 1 (FSCN1) gene, known to increase cell motility and directly related to EMT in lung adenocarcinoma cell lines." (PMID 36827545, 2023).
ovarian carcinoma (6 papers, 2016 to 2023). A malignant neoplasm originating from the surface ovarian epithelium. "Furthermore, the level of linc-ROR expression was associated with ovarian cancer International Federation of Gynecology and Obstetrics stage and lymph node metastasis." (PMID 29050257, 2017). "The filamin B (FLNB) gene was proved to be downregulated by linc-ROR by acting as a sponge for miR-145 in ovarian cancer." (PMID 36827545, 2023). "To investigate the oncogenic role of linc-ROR in ovarian cancer, we exogenously silenced or overexpressed linc-ROR in ovarian cancer cells using siRNA, or lentivirus and expression plasmids." (PMID 29050257, 2017). "To investigate the oncogenic role of linc-ROR in ovarian cancer EMT, we detected EMT marker expression via western blotting." (PMID 29050257, 2017). "We then investigated the functions of linc-ROR in ovarian cancer cell proliferation both in vitro and in vivo, and its roles in cell invasion and metastasis." (PMID 29050257, 2017). "We demonstrate that the linc-ROR-induced changes in EMT in ovarian cancer cell lines are the result of alterations in the canonical Wnt/β-catenin signaling pathway." (PMID 29050257, 2017). "In our study, we found that linc-ROR was associated with expression of the EMT-associated markers E-cadherin, vimentin, β-catenin, and c-myc in ovarian cancer cells." (PMID 29050257, 2017). "Linc-ROR also showed a trend of increasing expression in patients with more advanced clinical phases of ovarian cancer (P<0.01), while patients with lymph node metastases had higher linc-ROR expression than those without (P<0.01)." (PMID 29050257, 2017). "We also detected upregulated β-catenin and c-myc in exogenously overexpressing linc-ROR cells compared with control cells, providing further evidence that linc-ROR induces EMT in ovarian cancer cells." (PMID 29050257, 2017). "We next investigated the biological effects of linc-ROR on the migration and invasion of ovarian cancer cells." (PMID 29050257, 2017). "Linc-ROR promoted ovarian cancer cell proliferation both in vitro and in vivo, and contributed to cell migration and invasion." (PMID 29050257, 2017). "Further experimentation confirmed that linc-ROR triggered ovarian cancer cells to undergo EMT through Wnt/β-catenin pathway activation." (PMID 29050257, 2017). "Other lncRNAs have also been shown to be associated with ovarian cancer development and metastasis, including HOTAIR, H19, GAS5, and UCA1; however, to date, little was known about linc-ROR in ovarian cancer." (PMID 29050257, 2017). "This study identified an oncogenic role for linc-ROR in ovarian cancer development and metastasis." (PMID 29050257, 2017). "Together, these results suggest that linc-ROR may be an important regulator of proliferation in ovarian cancer cells in vitro." (PMID 29050257, 2017). "Therefore, we conclude that linc-ROR promotes ovarian cancer EMT at least in part by activating the Wnt/β-catenin pathway." (PMID 29050257, 2017). "Moreover, exogenously upregulating linc-ROR expression in ovarian cancer cells promoted proliferation, migration, and invasion in vitro, and promoted tumor growth in immunodeficient mice in vivo." (PMID 29050257, 2017). "To determine whether linc- ROR could regulate tumorigenesis of ovarian cancer cells in vivo, we performed assays in immunodeficient mice." (PMID 29050257, 2017). "We hypothesized that linc-ROR may have triggered an EMT program in ovarian cancer cells by upregulating Wnt/β-catenin signaling." (PMID 29050257, 2017). "Analysis of suggested that patients with more advanced ovarian cancer (those with an advanced FIGO stage) have increased tumoral linc-ROR expression; furthermore, linc-ROR expression was higher in ovarian cancer tissues from patients with than without lymph node metastases." (PMID 29050257, 2017). "Thus, we conclude that linc-ROR mediates the invasion and metastasis of ovarian cancer cells at least in part by activating EMT through Wnt/β-catenin signaling." (PMID 29050257, 2017).
ovarian carcinoma (continued). "Similarly, linc-ROR induced EMT in ovarian cancer cells by activating the Wnt/β-catenin cascade." (PMID 36827545, 2023). "Moreover, linc-ROR induces EMT in ovarian cancer cells by increasing Wnt/β-catenin signaling." (PMID 34690755, 2021). "Furthermore, we showed that linc-ROR acts as a potential oncogene in ovarian cancer by initiating an EMT program, and that the Wnt/β-catenin pathway may also be involved in this process." (PMID 29050257, 2017). "Ectopically expressed linc-ROR promoted proliferation in vitro and in vivo, contributed to cell migration and invasion, and inhibited the epithelial marker E-cadherin, while stimulating expression of the mesenchymal marker vimentin in an ovarian cancer cell line." (PMID 29050257, 2017). "Linc-ROR knockdown in ovarian cancer cell lines inhibited the epithelial-to-mesenchymal transition (EMT) program, which led to ovarian cancer cell metastasis through the repression of canonical Wnt/β-catenin signaling." (PMID 29050257, 2017). "Therefore, linc-ROR may be a key regulator of ovarian cancer EMT and metastasis." (PMID 29050257, 2017). "This study explored a new regulatory mechanism for linc-ROR in ovarian cancer invasion and metastasis, and provides new evidence for the therapeutic and prognostic value of linc-ROR in ovarian cancer." (PMID 29050257, 2017). "However, little is known about whether linc-ROR has a role in ovarian cancer progression." (PMID 29050257, 2017). "Similarly, linc-ROR expression in the plasma was closely related to FIGO stage, tumor grade, and lymph node metastasis in 60 cases of ovarian cancer patients." (PMID 36827545, 2023). "In this regard, a former study has examined the expression of LINC-ROR in various cell lines and human tumor tissue samples and reported that the expression of LINC-ROR increases in cervical, esophageal, and ovarian cancers, but decreases in breast, colon, sarcoma and melanoma cancers." (PMID 33745265, 2021). "Knockdown of Linc-ROR in ovarian cancer cell lines prevents EMT processes through the repression of Wnt/β-catenin signaling; the results suggest that EMT can be an important phenomenon in the invasion and metastasis of ovarian cancer." (PMID 29780815, 2018). "Together, our results indicated that linc-ROR induces EMT in ovarian cancer cells and may be an important molecule in the invasion and metastasis of ovarian cancer." (PMID 29050257, 2017). "However, the relationship between linc-ROR and EMT in ovarian cancer progression and metastasis remains unknown." (PMID 29050257, 2017). "To further investigate the effects of linc-ROR on the biological functions of ovarian cancer cells, we exogenously decreased linc-ROR expression by transfecting small interfering (si)-linc-ROR, and increased linc-ROR expression by transfecting the pIRES2-EGFP-linc-ROR vector." (PMID 29050257, 2017).
breast tumor (5 papers, 2018 to 2021). "The RT–qPCR results revealed that the expression of linc‐ROR was significantly upregulated in breast tumor tissues compared with paracarcinoma tissues (P < 0.0001)." (PMID 32335998, 2020). "High LINC-ROR expression in breast tumors was associated with reduced OS, and knockdown of LINC-ROR inhibited TGFβ signaling in MCF-7 and MDA-MB-231 cells." (PMID 30545127, 2018). "Finally, we found that linc‐ROR was upregulated in breast tumor tissues." (PMID 32335998, 2020). "LINC-ROR expression was higher in breast tumors and cell lines relative to normal breast tissue, and MCF-10A cells and the overexpression of LINC-ROR induced markers of EMT in MCF-10A cells." (PMID 30545127, 2018).
lung carcinoma (5 papers, 2017 to 2025). "LINC-ROR is upregulated in lung cancer stem cell and non-small cell lung cancer and associated with poor prognosis." (PMID 33745265, 2021). "In lung cancer, lncRNA linc-ROR sponges miR-145, derepressing fascin and promoting EMT and resistance, which is reversible upon knockdown." (PMID 40806254, 2025). "In recent years, linc-ROR has appeared as an important regulator of lung cancer." (PMID 32850817, 2020).
schizophrenia (4 papers, 2019 to 2022). A major psychotic disorder characterized by abnormalities in the perception or expression of reality. "A former study has shown sex-specific dysregulation of HOXA-AS2, Linc-ROR, MEG3, SPRY4-IT1 and UCA1 lncRNAs in patients with schizophrenia." (PMID 35410190, 2022). "We have demonstrated up-regulation of HOXA-AS2, Linc-ROR, MEG3, SPRY4-IT1, and UCA1 in patients with schizophrenia compared with healthy subjects." (PMID 34220567, 2021). "While Gomafu, PINT, GAS5, TCONS_l2_00021339, IFNG-AS1, FAS-AS1, PVT1, and TUG1 are among down-regulated lncRNAs in schizophrenia, MEG3, THRIL, HOXA-AS2, Linc-ROR, SPRY4-IT1, UCA1, and MALAT1 have been up-regulated in these patients." (PMID 34220567, 2021). "We selected six lncRNAs namely HOXA-AS2, Linc-ROR, MEG3, SPRY4-IT1, UCA1 and MALAT1 to assess their expression in peripheral blood of patients with schizophrenia and healthy subjects." (PMID 31484957, 2019). "Based on the acknowledged roles of lncRNAs in neurodevelopment, in the current study, we assessed expression of six lncRNAs namely HOXA-AS2, Linc-ROR, MALAT1, MEG3, SPRY4-IT1 and UCA1 in peripheral blood of 60 patients with schizophrenia and 60 healthy subjects." (PMID 31484957, 2019).